SOD1 (superoxide dismutase 1)
Diseases named in the same sentence as SOD1 in open-access papers (continued):
Sharing a sentence is not in itself a finding about the gene and the disease.
motor neuron disease (continued). "Moreover, transgenic mouse models expressing mutant and wtTDP-43 frequently do not exhibit the robust motor neuron disease observed in transgenic human mutant SOD1 mice, or in SOD1-FALS patients." (PMID 26926802, 2016). "Motor neuron disease in mutant SOD1-mediated ALS is a non-cell autonomous process." (PMID 22523565, 2012). "Furthermore, the absence of TNF-α failed to ameliorate motor neuron disease in SOD1 TG mice." (PMID 27070121, 2016).
familial amyotrophic lateral sclerosis (119 papers, 2006 to 2025). An instance of amyotrophic lateral sclerosis that is caused by an inherited modification of the individual's genome. "Sequencing kernel association test analysis showed that the SOD1 rare variant burden (P = 1.3e-15) was associated with a significant risk of familial amyotrophic lateral sclerosis." (PMID 41673790, 2025). "Accumulation of misfolded SOD1 and tau proteins are considered to be causatively associated with the pathogenesis of hereditary amyotrophic lateral sclerosis and tauopathies, respectively." (PMID 38815862, 2024). "Mutations in the Cu-Zn superoxide dismutase 1 gene SOD1 can cause familial amyotrophic lateral sclerosis (fALS) in a process that involves dissociation of the SOD1 dimer." (PMID 38289969, 2024). "Mutations in the gene encoding Cu-Zn superoxide dismutase 1 (SOD1) cause a subset of familial amyotrophic lateral sclerosis (fALS) cases." (PMID 38289969, 2024). "The mechanisms involved in clearing white matter, such as ubiquitin, are closely associated with SOD1 aggregates in SOD1-familial amyotrophic lateral sclerosis (FALS) and PD." (PMID 38715962, 2024). "We observed a Polish family with familial amyotrophic lateral sclerosis with heterozygous L144S SOD1 mutation, which manifested clinically as flail leg syndrome." (PMID 37034065, 2023). "Although familial amyotrophic lateral sclerosis is usually associated with a worse prognosis than the sporadic form of the disease, the clinical course of the disease in patients with L144S SOD1 mutation is benign, with slow progression and long survival." (PMID 37034065, 2023). "Here we provide evidence demonstrating pathogenic differences in CSF from patients with sporadic amyotrophic lateral sclerosis and familial amyotrophic lateral sclerosis patients with mutations in SOD1, C9orf72 and TARDBP." (PMID 36043141, 2022). "Monomerization increases the likelihood of SOD1 misfolding into conformations associated with aggregation, cellular toxicity, and neuronal death in familial amyotrophic lateral sclerosis (fALS)." (PMID 35402516, 2022). "The formation of SOD1 monomer leads to a decrease in its activity and is an early step in SOD1 aggregation, which causes familial amyotrophic lateral sclerosis (fALS)." (PMID 34986524, 2022). "For example, mutations in the gene superoxide dismutase 1 (SOD1) lead to familial amyotrophic lateral sclerosis (fALS)." (PMID 34322024, 2021). "These mice are widely used to model SOD1‐linked familial amyotrophic lateral sclerosis, and to investigate how SOD1 mutations alter SOD1 biochemistry and contribute to motor neuron degeneration in this disorder." (PMID 32144830, 2021). "Several mutations in the Cu/Zn superoxide dismutase gene (SOD1) cause familial amyotrophic lateral sclerosis (FALS)." (PMID 34177463, 2021). "Mutations in Cu/Zn superoxide dismutase 1 (SOD1) associated with familial amyotrophic lateral sclerosis cause the protein to aggregate via a prion-like process in which soluble molecules are recruited to aggregates by conformational templating." (PMID 31999698, 2020). "Mutations of the superoxide dismutase 1 (SOD1) protein have been linked to another neurodegenerative disease that affects motility (familial amyotrophic lateral sclerosis)." (PMID 32714204, 2020). "Mutations in the gene encoding the enzyme copper/zinc (Cu/Zn) SOD1 were the first mutation identified to be associated with familial amyotrophic lateral sclerosis (ALS)." (PMID 31665015, 2019). "While SOD2 and SOD3 have had little published linkage to disease, SOD1 has been associated with Familial Amyotrophic Lateral Sclerosis (fALS), and SOD1 is implicated in apoptosis." (PMID 31380411, 2019). "Mutations in superoxide dismutase 1 (SOD1) associated with familial amyotrophic lateral sclerosis (fALS) induce the protein to misfold and aggregate." (PMID 30399166, 2018).
familial amyotrophic lateral sclerosis (continued). "It is also known that about 20% of familial amyotrophic lateral sclerosis (fALS) is due to mutations in the gene coding for SOD1." (PMID 29881358, 2018). "On the other hand, accumulation of free radicals as a result of defective enzyme function can lead to neurotoxicity, as it happens in SOD1 mutation associated familial amyotrophic lateral sclerosis, or to malignant transformation in different tissues." (PMID 29507682, 2018). "Over 160 mutations in superoxide dismutase 1 (SOD1) are associated with familial amyotrophic lateral sclerosis (fALS), where the main pathological feature is deposition of SOD1 into proteinaceous cytoplasmic inclusions." (PMID 30349065, 2018). "Mutations in superoxide dismutase 1 (SOD1) are linked to familial amyotrophic lateral sclerosis (fALS); these mutations result in progressive motor neuron death through one or more acquired toxicities." (PMID 26878886, 2016). "Superoxide dismutase 1 (SOD1) has been implicated with familial amyotrophic lateral sclerosis (fALS) through accumulation of protein amyloid aggregates in motor neurons of patients." (PMID 27695694, 2016). "Identification of mutations in SOD1 gene as causative ones in familial amyotrophic lateral sclerosis (fALS) was immediately followed by the generation of transgenic mice constitutively overexpressing mutated human SOD1." (PMID 26778957, 2015). "While mutations in SOD1 is the cause of 20% of cases of familial amyotrophic lateral sclerosis (fALS), a devastating neurodegenerative disease, these new studies expand the role of SOD1 to cancer." (PMID 24955214, 2014). "Dying-back degeneration of motor neuron axons represents an established feature of familial amyotrophic lateral sclerosis (FALS) associated with superoxide dismutase 1 (SOD1) mutations, but axon-autonomous effects of pathogenic SOD1 remained undefined." (PMID 23776455, 2013). "Although mutations in human SOD1 are associated with familial amyotrophic lateral sclerosis (fALS), Sod1 deficient mice are neurologically normal and do not develop spontaneous neurodegenerative disease." (PMID 23349894, 2013). "Mutations in the gene encoding superoxide dismutase 1 (SOD1) cause ∼20% of the cases of familial amyotrophic lateral sclerosis (fALS)." (PMID 24391857, 2013). "Mutations in the gene encoding superoxide dismutase 1 (SOD1) account for about 20% of the cases of familial amyotrophic lateral sclerosis (fALS)." (PMID 24341866, 2013). "Mutations in Cu/Zn superoxide dismutase gene (SOD1) are associated with familial amyotrophic lateral sclerosis." (PMID 22829832, 2012). "Protein disulfide isomerase was found to be associated with SOD1 in cellular and animal models of familial amyotrophic lateral sclerosis, a neurodegenerative disease affecting motor neurons." (PMID 23061969, 2012). "Pathologic aggregates of superoxide dismutase 1 (SOD1) harboring mutations linked to familial amyotrophic lateral sclerosis (fALS) have been shown to contain aberrant intermolecular disulfide cross-links." (PMID 23118898, 2012). "Cu/Zn superoxide dismutase (SOD1) is a major component of Lewy body-like hyaline inclusion (LBHI) found in the postmortem tissue of SOD1-linked familial amyotrophic lateral sclerosis (FALS) patients." (PMID 21655264, 2011). "Mutations in the gene encoding Cu-Zn superoxide dismutase (SOD1) are one of the causes of familial amyotrophic lateral sclerosis (FALS)." (PMID 19325915, 2009). "Neuronal Lewy body-like hyaline inclusions (LBHI) and astrocytic hyaline inclusions (Ast-HI) containing mutant Cu/Zn superoxide dismutase 1 (SOD1) are morphological hallmarks of familial amyotrophic lateral sclerosis (FALS) associated with mutant SOD1." (PMID 17925878, 2007). "Mutations in SOD1 are associated with familial amyotrophic lateral sclerosis." (PMID 33834021, 2021).
familial amyotrophic lateral sclerosis (continued). "HECW1 was found to ubiquitinate familial amyotrophic lateral sclerosis (FALS)-linked superoxide dismutase-1 gene for degradation which might contribute to the pathogenesis of FALS." (PMID 31057023, 2019). "In human-derived astrocytes harboring mutant SOD1 causative of familial amyotrophic lateral sclerosis, we show that impaired ER redox signaling decreases Nrf2 nuclear translocation, resulting in ER calcium overload and increased calcium-dependent cell secretion, leading to motor neuron death." (PMID 31658977, 2019). "Of note, NEDL1 can bind and ubiquitinate mutant superoxide dismutase-1 (SOD1), the causal protein of familial amyotrophic lateral sclerosis (FALS), as results in the formation of potentially cytotoxic protein that aggregates in the spinal cord and consequent motor neuron death in FALS." (PMID 24709709, 2013). "By mechanisms yet to be discerned, the co-expression of high levels of wild-type human superoxide dismutase 1 (hSOD1) with variants of hSOD1 encoding mutations linked familial amyotrophic lateral sclerosis (fALS) hastens the onset of motor neuron degeneration in transgenic mice." (PMID 24391857, 2013). "In the present work, this issue has been approached by starting from a known attribute; that misfolded mutant SOD1 is linked to familial amyotrophic lateral sclerosis and utilizing a functional genomic approach to identify cellular proteins involved in regulation of this attribute." (PMID 22563406, 2012). "Furthermore, a biochemical interaction between PDI and SOD1 is implicated in the pathogenesis of familial amyotrophic lateral sclerosis." (PMID 23061969, 2012). "The discovery that mutations in SOD1 gene cause a subset of familial amyotrophic lateral sclerosis (FALS) has attracted great attention, and studies to date have been mainly focused on discovering mutations in the coding region and investigation at protein level." (PMID 21603028, 2011). "Furthermore, RNAi knockdown of SOD1 protein expression did not provide any additional rescue, indicating that our data are not confounded by toxicity caused by SOD1 misfolding and aggregation as is proposed for SOD1-linked familial amyotrophic lateral sclerosis." (PMID 19519625, 2009). "p62 and autophagy synergize to promote tumor growth, and p62 selectively binds mutant SOD1 to form aggregates in model systems of familial amyotrophic lateral sclerosis." (PMID 28536631, 2016). "Mutations in the superoxide dismutase 1 (SOD1) gene contribute to motoneuron degeneration and are evident in 20% of familial amyotrophic lateral sclerosis cases." (PMID 27257617, 2016). "Similar to the polyQ family of proteins, superoxide dismutase 1 (SOD1) is another protein whose aggregation is correlated with a neurodegenerative disease, in this case familial amyotrophic lateral sclerosis (FALS)." (PMID 22768276, 2012). "Mutations in superoxide dismutase 1 (SOD1), which are one cause of familial amyotrophic lateral sclerosis (fALS), induce misfolding and aggregation of the protein." (PMID 22094223, 2011). "SOD1 and NF1 and their homologues have appeared in our gene ontology search as linked with several types of myelopathies and familial amyotrophic lateral sclerosis." (PMID 21152067, 2010). "Another interesting study investigated whether ASC-Exo could protect motoneuron-like NSC-34 cells from oxidative damage, as well as an in vitro model of familial amyotrophic lateral sclerosis (fALS) (NSC-34 SOD1(G93A); NSC-34 SOD1(G37R); NSC-34 SOD1(A4V))." (PMID 38922501, 2024). "The HECW1 protein also ubiquitinates the mutant form of the superoxide dismutase (SOD1) enzyme in people with hereditary amyotrophic lateral sclerosis, binds to amyloid-sensitive epithelial sodium channels and possibly participates in the regulation of their activity." (PMID 36362280, 2022).
familial amyotrophic lateral sclerosis (continued). "Indeed, we demonstrated that GSH finely compensates the decline of SOD1 activity in: (i) cells expressing less active SOD1 mutant found in familial amyotrophic lateral sclerosis; (ii) cells in which SOD1 is down-regulated by RNA interference." (PMID 25206336, 2014). "However, familial amyotrophic lateral sclerosis (FALS) without superoxide dismutase-1 gene (SOD1) mutation is less heterogeneous than SALS." (PMID 21483737, 2011). "The present evidence supports a hypothesis that mitochondria are a target of mutant SOD1-mediated toxicity in familial amyotrophic lateral sclerosis (fALS) and intracellular alterations of cytosolic and mitochondrial calcium might aggravate the course of this neurodegenerative disease." (PMID 19545440, 2009). "Restoring neuronal copper levels can confer significant neuroprotection in PD and familial amyotrophic lateral sclerosis (FALS), potentially through stabilizing and enhancing the function of disease-relevant copper proteins, including SOD1." (PMID 38715962, 2024). "In familial amyotrophic lateral sclerosis (fALS), the IMS-fraction of SOD1, although a minor fraction of total cellular SOD1, appears to play an important role." (PMID 24955214, 2014). "Second, a physical interaction between SOD1 and PDI has been indicated in cultured cells in familial amyotrophic lateral sclerosis." (PMID 23061969, 2012). "Anti-sense oligonucleotides in familial amyotrophic lateral sclerosis (fALS): In the brain and spinal cord of SOD1-rats, it was shown that intracerebroventricular injections of ASO against SOD1 directly decreased SOD1 mRNA through RNase H activity, extending the rats' mean lifetime by 10 days." (PMID 38090405, 2023). "In 2013, the first phase 1 human trial of an intrathecally delivered ASO, targeting superoxide dismutase 1 (SOD1) in familial amyotrophic lateral sclerosis, was completed without significant safety issues reported, paving the way for such trials with such agents in HD." (PMID 25155142, 2014). "However, according to Decipher, no cases of SOD-1 deletions (chr21:31659622–31668930, hg38) have been associated with tremor until now and the unique family with SOD-1 null mutation manifested an atypical form of familial amyotrophic lateral sclerosis." (PMID 27625702, 2016).
breast carcinoma (116 papers, 2006 to 2025). "Studies have shown that SOD1 is overexpressed in various types of cancer, including breast cancer, and its overexpression has been associated with tumour growth, invasion, and metastasis." (PMID 38227157, 2024). "Aggregation of superoxide dismutase (SOD1) causes cell death in ALS; however, SOD1 also has a role in breast cancer and the ability to increase estrogen reactive gene expression." (PMID 34073579, 2021). "Numerous cancers express high level of SOD1, including lung adenocarcinoma, breast cancer, and leukemia, and its elevated expression is associated with poor survival." (PMID 32391354, 2020). "In this regard, it has been determined that the expression of miR-3689a-3p significantly reduced the resistance of breast cancer cells to sorafenib by abrogating SOD1-mediated mitochondrial oxidative stress, which ultimately increased HCC cell death." (PMID 40061926, 2025). "Several pieces of evidence, including high intracellular Cu levels and SOD1 expression levels in many breast cancer cells, including MDA-MB-231 cells, as well as their protective effects on cells through ROS removal, support the findings of the present study." (PMID 40570957, 2025). "No relevant data are available in literature on the effect of AtRA, a cognate ligand of RARs, on the SOD1 or SOD2 expression in human breast cancer cell lines." (PMID 38227157, 2024). "These promising findings were further confirmed in cell line studies, highlighting the therapeutic potential of targeting SOD1 in breast cancer management." (PMID 39123408, 2024). "Glutathione S-transferase Mu 3 (GSTM3) is another antioxidant overexpressed in MCF-7 breast cancer cells, while superoxide dismutase (SOD1) was overexpressed in PC3 prostate cancer cells." (PMID 38249992, 2024). "Recent studies showed that breast cancer cell-derived survivin upregulates the expression of SOD1 in fibroblasts and subsequently transforms it into myofibroblasts, which in turn induces breast cancer progressionin vitro andin vivo." (PMID 38516703, 2024). "Even with this type of tumor, research has focused on the study of pharmacological molecules aimed at inhibiting the overexpression of SOD1 in breast cancer cells." (PMID 39123408, 2024). "In previous studies, SOD1 has found to be overexpressed in numerous cancers like NSCLC, leukemia and breast cancer, the overexpression is linked to poor survival of cancer cell." (PMID 36809279, 2023). "For example, drugs that inhibit SOD1 can potentially be used for the treatment of cancers in which SOD1 is overexpressed, such as non-small cell lung cancer and breast cancer." (PMID 37371889, 2023). "Breast cancer cell-derived Survivin upregulates SOD1 expression in fibroblasts and converts them into myofibroblasts, conversely inducing breast cancer progression in vitro and in vivo." (PMID 36499561, 2022). "Research has revealed that sEVs from breast cancer samples increase superoxide dismutase 1 (SOD1) expression in fibroblasts, which are then converted into myofibroblasts (CAF-like)." (PMID 36096820, 2022). "The exosomal transfer of cervical cancer Wnt2B activates Wnt/β-catenin signaling to activate fibroblasts into CAFs while survivin from breast cancer induces CAFs through SOD1 upregulation." (PMID 35052791, 2022). "SOD1 carries a housekeeping function that maintains ROS levels below a threshold, supporting oncogene-dependent proliferation in mammary tumor formation." (PMID 35874705, 2022). "Breast cancer-derived exosomal survivin converts fibroblasts into myofibroblasts by upregulating SOD1." (PMID 34853307, 2021). "For example, expression of the copper/zinc dismutase SOD1 is dispensable for normal mammary gland development, yet is essential for the survival of breast cancer cells." (PMID 34411095, 2021).